CRP (C-reactive protein)
Diseases named in the same sentence as CRP in open-access papers (continued):
Sharing a sentence is not in itself a finding about the gene and the disease.
bacterial infection (continued). "The determination of CRP values is well-established in routine clinical practice as a marker of bacterial infections." (PMID 35204585, 2022). "Procalcitonin (PCT) and C- reactive protein (CRP) have both been widely used as biomarkers implying bacterial infections due to their predictable kinetics, appropriate half-life, and high specificity." (PMID 35149284, 2022). "CRP is a real-time and low-cost biomarker that serves as a screening tool in the emergency department (ED), and a high CRP concentration is indicative of a bacterial infection." (PMID 36477474, 2022). "It performed much better to help to diagnose bacterial infection than other inflammatory biomarkers such as CRP, PCT, and IL-10." (PMID 35391735, 2022). "C-reactive protein (CRP) is an established serum biomarker of bacterial infections in newborn infants, children, and adults." (PMID 36501194, 2022). "The area under the ROC curve (AUC) for a single CRP test to diagnose bacterial infection in NICU patients was 0.75 (95%CI: 0.61–0.89)." (PMID 36517750, 2022). "We applied estimated C-reactive protein (CRP) velocity (eCRPv), as derived from the admission CRP level divided by time from symptom onset, in order to better distinguish between viral and bacterial infections." (PMID 36477474, 2022). "The simultaneous quantification of PCT and CRP can enable the early detection of bacterial infections." (PMID 35149284, 2022). "Nevertheless, the validity of our computational approach was supported by the better diagnostic performance achieved in the subgroup of patients with proven bacterial infection (e.g., LR+ = 20.43, LR− = 0.25 for 5CV/CRP/TRAIL; post hoc analysis)." (PMID 36362791, 2022). "The serum SAA, PCT and CRP levels in the bacterial infection group were higher than those in the non-bacterial infection group and healthy children, and the differences were statistically significant." (PMID 35775463, 2022). "This spike in CRP velocity cannot be explained just by the natural course of bacterial infections, and a possible explanation for this dynamic is the administration of antibiotics between the first and second CRP tests." (PMID 35897672, 2022). "Patients diagnosed with a bacterial infection had a median CRP of 63 mg/L and CRPv of 3.61 mg/L/h, and patients with a non-bacterial diagnosis had a median CRP of 23 mg/L and CRPv of 0.41 mg/L/hour." (PMID 35897672, 2022). "High levels of CRP are related to bacterial infections and some viral infections like Hemagglutinin 1 Neuraminidase 1 (H1N1) and Corona Virus Disease 2019 (COVID-19)." (PMID 35144683, 2022). "This determination of IL-6 is helpful for the early evaluation and diagnosis of bacterial infection, and its sensitivity and specificity are higher than those of CRP in current clinical use." (PMID 35432366, 2022). "All participants received GBC and CRP according to the local viral/bacterial infection diagnostics algorithm." (PMID 36362702, 2022). "On-CRP plays roles in bacterial agglutination, phagocytosis, and modulating inflammation during bacterial infection." (PMID 36009776, 2022). "Patients with significantly elevated CRP velocities should be hospitalized and monitored carefully, and, in case bacterial infections are suspected, they should be given antibiotic treatment as soon as possible." (PMID 35897672, 2022). "The performance of the absolute CRP value to diagnose bacterial infection varied according to time from symptoms." (PMID 36517750, 2022). "Inflammatory biomarkers such as CRP can aid confirm the clinical suspicion of invasive bacterial infection and optimize and tailor antibiotic therapy." (PMID 35655792, 2022). "In human medicine, there used to be an outdated generalization that high CRP blood concentration is a marker of somewhat specificity for bacterial infections." (PMID 36290272, 2022).
bacterial infection (continued). "In clinical practice, early diagnosis of a bacterial infection which require antibiotic treatment is most frequently based on observation of clinical symptoms, supplemented with leukocyte counts and/or C-reactive protein (CRP) measurement in blood." (PMID 35102763, 2022). "Our current study addresses the dynamics of CRP by determining eCRPv values with the aim of discriminating between viral and bacterial infections." (PMID 36477474, 2022). "Compared to white blood cell count and procalcitonin level, the C-reactive protein level was the best performing inflammatory marker for predicting bacterial infection, even though its sensitivity and specificity were low." (PMID 35203787, 2022). "Since the physiological concentration of CRP in healthy individuals is often < 1 mg/dL, the CRP concentration detected here strongly suggested the capability of the duplex to probe fluctuations levels of CRP during bacterial infections." (PMID 35149284, 2022). "The positive detection rates and combined detection rates of serum SAA, PCT and CRP in the bacterial infection group were higher than those in the non-bacterial infection group and the healthy subject's control group." (PMID 35775463, 2022). "The major limitation of CRP is its low specificity in differentiating bacterial infection from autoimmune diseases and some haematological malignancies." (PMID 35500008, 2022). "Because CRP is more significantly increased due to bacterial infections than the viral ones, CRP tests serve for the decision of antibiotics prescription." (PMID 35624645, 2022). "We demonstrated its usefulness for patients with low levels of CRP upon admission, among whom a high rate of the development of an acute response over time is indicative of a bacterial infection." (PMID 36477474, 2022). "When compared with CRP, procalcitonin is detectable in serum 3 hours after a bacterial infection and peaks 6–12 hours later, whereas CRP peaks at 36–50 hours." (PMID 35476639, 2022). "CRP test was positive in 84.3% (334/396) of the children, but bacterial infections were confirmed in 12.4% (49/396) of them." (PMID 36536340, 2022). "Laboratory parameters are usually altered, with elevated leukocytes and C-reactive protein or erythrocyte sedimentation rate, consistently with a bacterial infection." (PMID 35448708, 2022). "A single CRP test and CRP velocity performed similarly in diagnosing bacterial infection, with area under ROC curve of 0.75 (95%CI: 0.61–0.89) and 0.77 (95% CI:0.66–0.88), respectively." (PMID 36517750, 2022). "Some other studies documented that PCT and CRP are more appropriate markers for bacterial infection detection in patients with decompensated LC." (PMID 36140479, 2022). "A recently published study by our lab showed the ability of those kinetics between 2 consecutive CRP measurements to distinguish between viral and bacterial infections." (PMID 36477474, 2022). "CRP > 1.5 mg/dL, obtained > 6 hours from symptoms onset, was 100% sensitive to diagnose bacterial infection, at a cost of relatively low specificity." (PMID 36517750, 2022). "suPAR was of limited specificity for the diagnosis of bacterial infections and inferior to both procalcitonin and CRP." (PMID 36420338, 2022). "The levels of serum SAA, PCT and CRP in the bacterial infection group were 281.34 ± 42.45, 3.28 ± 1.01 and 42.67 ± 11.02 respectively." (PMID 35775463, 2022). "For example, the difference between two CRP measurements has been used to distinguish between viral and bacterial infections." (PMID 36477474, 2022). "The transcriptional levels of On-CRP were significantly promoted (p < 0.05) in all examined tissues (brain, head kidney, intestine, liver, and spleen) post bacterial infection." (PMID 36009776, 2022). "The benefits of rapid or bedside CRP measurement are most clear for acute inflammatory conditions such as bacterial infection." (PMID 36458039, 2022).
bacterial infection (continued). "Generally, both CRP and PCT perform better than WBC, while in the youngest children with serious bacterial infection PCT outperforms CRP in the very first hours from fever onset, but with much higher cost." (PMID 35359908, 2022). "Three out of 4 patients needing IMV and treated with anakinra were successfully extubated.Ferritin and CRP dropped down or normalized during anakinra treatment in all but one patient.Bacterial infections and elevation of transaminases occurred in 3 patients." (PMID 36209522, 2022). "Hepatic synthesis of the acute phase protein CRP as a response to bacterial infection takes place after stimulation by IL-6 and other proinflammatory cytokines." (PMID 35345614, 2022). "The present data lays a theoretical foundation to further explore the mechanism of how CRP protects fish against bacterial infection." (PMID 36009776, 2022). "CRP values of 20–40 mg/L were recorded in both viral and bacterial infections and most febrile children with CRP ≥40 mg/L had a bacterial infection." (PMID 36333682, 2022). "One study found that a serum CRP cut-off value of 60 mg/L was the best predictor for early detection of bacterial infections, including UTIs, in an older hospitalised population." (PMID 35255822, 2022). "The optimal cut-off value for a CRP test obtained <= 6 hours from symptoms onset to diagnose bacterial infections, was 1 mg/dL, whereas the optimal cut-off > 6 hours from symptoms onset was 1.5 mg/dL." (PMID 36517750, 2022). "POC CRP has demonstrated high discriminatory power in distinguishing viral from bacterial infections and can be combined with MxA to increase sensitivity, specificity, and overall accuracy." (PMID 36010008, 2022). "Comparison of serum SAA, PCT and CRP levels before and after treatment in bacterial infection group." (PMID 35775463, 2022). "The hepatic acute phase reactant CRP is the most commonly used biomarker of bacterial infections, which is also recommended by the febrile neutropenia guideline of the European Society of Medical Oncology (ESMO)." (PMID 36095013, 2022). "In this study, a CRP gene from Nile tilapia (On-CRP) was identified, and its roles in response to bacterial infection were investigated in vivo or in vitro." (PMID 36009776, 2022). "In an ROC analysis, the blood MxA (μg/L) to CRP (mg/L) ratio gave the AUC of 0.89 (95% CI = 0.83 to 0.96) for differentiation between viral and bacterial infections." (PMID 35080443, 2022). "Our results showed that both PCT and CRP are more sensitive than specific in the diagnosis of bacterial infections in patients undergoing HD." (PMID 35164633, 2022). "Mean CRP in these patients was 2.47 ± 3.3 mg/dL, the area under the ROC curve was 0.66 (95%CI: 0.66–0.8) and CRP of 1 mg/dL had only 50% sensitivity and 74% specificity to diagnose “possible” bacterial infection." (PMID 36517750, 2022). "First, neither the VAT nor the SAT area correlated with systemic inflammation indicated by the C-reactive protein (CRP), interleukin 6 (IL-6) or bacterial infections indicated by procalcitonin (PCT)." (PMID 33861804, 2021). "Some bacterial infections can dramatically increase CRP levels up to 1,000-fold in the span of 24–72 hours." (PMID 34925360, 2021). "In this study, we found that, among the selected biomarkers, CRP had the best accuracy in differentiating viral from bacterial infections." (PMID 34574070, 2021). "Kawasaki disease shock syndrome less than 5% of children with KD present with bacterial disease-like shock and hypotension and have higher neutrophil and band counts, lower platelet counts, lower hemoglobin levels, and higher CRP levels compared to KD." (PMID 34773697, 2021). "As an acute phase response protein, CRP has been reported to be elevated in the early phase of bacterial infections, which was consistent with our findings." (PMID 33732661, 2021).
bacterial infection (continued). "From the results—increased WBC (10,210 per μL with a left shift) and CRP (5.65 mg/dL)—the patient was assessed to have an acute bacterial infection." (PMID 34468333, 2021). "The observed accuracy of PCT, CRP and white blood cell counts (approved for the detection of bacterial infections) ranged from 0.78 to 0.88." (PMID 34142256, 2021). "Antibiotics are added when a super-added bacterial infection is suspected either clinically or positive cultures with high lab markers like CRP and procalcitonin." (PMID 33718282, 2021). "PCT and CRP are well-known markers of bacterial infections, and can be used to predict increased mortality rate in critically ill patients." (PMID 33437244, 2021). "In our study, a significant increase in both PCT and CRP levels was observed in patients with secondary bacterial infection." (PMID 34021897, 2021). "Both PCT and CRP are commonly used clinical markers of inflammation and used for differential diagnosis and monitoring of bacterial infectious diseases." (PMID 34233608, 2021). "Other studies tried to use the kinetics of CRP for the microbial etiology diagnosis, specifically in the early discrimination between acute viral and bacterial infections." (PMID 34863104, 2021). "In contrast, other studies have reported that CRP level >40 mg/dL indicate severe bacterial infection, can be used as a predictor of renal scarring associated with a first urinary tract infection, and indicate acute pyelonephritis in the pediatric field." (PMID 33606735, 2021). "The median CRP values of viral and bacterial infections were 8.00 (IQR: 8.00–16.00) and 122 (IQR: 51.00–225.00) mg/L, respectively (p < 0.001)." (PMID 34574070, 2021). "Of note, seroconversion is not strongly correlated with changes in acute phase proteins that are commonly elevated upon viral and bacterial infections, such as C-reactive protein (CRP) and ferritin (FTL)." (PMID 33724185, 2021). "The common features extracted in the ML models based on the adopted parameters were of reasonable relevance, as CRP, neutrophil, and band counts were reported to have a positive correlation with bacterial infections in young infants." (PMID 33925973, 2021). "Together, the increase of CRP levels in CLD patients are mainly attributed to the bacterial infection in our study; therefore, we used bacterial products to stimulate THP-1 and primary cells in the subsequent experiments." (PMID 34571946, 2021). "The primary aim of this study was to determine the discriminative ability of PCT, aPTT waveform, NGAL and resistin individually, in combination and compared to CRP to diagnose serious bacterial infection (SBI) in children on admission to PICU." (PMID 33544738, 2021). "Some infants had fever, with increased neutrophils, C-reactive protein, and procalcitonin levels, suggesting the presence of other bacterial infections." (PMID 33546645, 2021). "Conventional blood biomarkers, such as white blood cell (WBC) counts and C-reactive protein (CRP), have been widely used for diagnosing bacterial infections." (PMID 34066811, 2021). "Bacterial infection, Child–Pugh C classification, serum C-reactive protein, IL-6, percentages of cMo, iMo, and TiMas within the monocyte compartment, percentage of CD62L+ monocytes, and pDC/cDC ratio were associated with 90-day mortality." (PMID 33723292, 2021). "Consistent with their expected distributions, subjects with bacterial infections had higher concentrations of CRP and lower concentrations of TRAIL and IP-10." (PMID 34905580, 2021). "We assessed the diagnostic accuracy of PCT, CRP and WCC to diagnose bacterial infections in 65 neonatal and pediatric ECMO runs." (PMID 35155322, 2021). "TNF-α and CRP (C-reactive protein) underwent an initial increase (probably due to bacterial infection), followed by a clear reduction." (PMID 34572185, 2021).
bacterial infection (continued). "C-reactive protein and procalcitonin increased in 16.85% and 5.98% of the patients, respectively, suggesting the presence of other bacterial infections." (PMID 33546645, 2021). "IL-6 is a primary determinant of hepatic production of CRP and plays a key role in acute-phase inflammatory responses to for example viral or bacterial infections." (PMID 33948158, 2021). "Another showed the combination of tumor factor-related apoptosis-induced ligand (TRAIL), γ-induced protein-10 (IP-10), and C-reactive protein can differential bacterial infection from a viral process." (PMID 35096705, 2021). "It has been confirmed that the CRP levels increased during bacterial infection and thus CRP was considered as a marker for inflammation." (PMID 34362428, 2021). "On the other hand, a previous study showed that CRP at a cut-off of 10 mg/L had high sensitivity for the detection of bacterial infections (95%, 95% CI 92–97), while specificity was extremely low (49%, 95% CI 46–53)." (PMID 34574070, 2021). "Intravenous antibiotics were started on suspicion of secondary bacterial infection like persistence of high-grade fever, leucocytosis, high CRP, and deteriorating clinical condition." (PMID 35003977, 2021). "Frequently, CRP is considered helpful for the physician to differentiate viral from bacterial infection." (PMID 34306103, 2021). "CRP concentration exceeding 100 mg/L (often over 500 or 1000 mg/L) is usually found in serious bacterial infections." (PMID 33924694, 2021). "To date, there is no reliable biomarker to predict the favorable evolution during bacterial infection in the long run, however, a 2-fold decrease in the CRP level or an 80% reduction in the PCT value during follow-up is recognized as a strong argument." (PMID 34649512, 2021). "CRP levels have been previously recognized for their ability to identify or indicate febrile children with bacterial infection." (PMID 33481812, 2021). "The time of highest PCT and CRP levels correspond with the diagnosis of secondary bacterial infection." (PMID 34021897, 2021). "Biomarkers, especially CRP, have demonstrated their relevance to differentiate viral from bacterial infection, even though a reliable threshold is far to being found." (PMID 34574070, 2021). "In our previous study, TIMP-1 correlated with the total BVAS score before treatment and was less likely to be elevated in bacterial infections than CRP." (PMID 33743769, 2021). "CRP levels were also significantly higher in patients with bacterial infection but the cut-off value between both groups was with 172 mg/L considerably elevated (< 5 mg/L) and the predictive values slightly less robust." (PMID 34021897, 2021). "This suggests that in clinical practice, in addition to bacterial infection, the possibility of fungal sepsis should be considered for patients with significantly abnormal serum CRP and PCT levels." (PMID 34234782, 2021). "The primary objective of this study is to assess the best CRP cut-off to distinguish viral from bacterial infections." (PMID 34574070, 2021). "Our findings are in line with a recent meta-analysis and individual patient data study, which showed that a CRP cut-off close to the one found here (10 mg/L) achieved very high sensitivity for bacterial infections." (PMID 34574070, 2021). "This highlights the difficulty for physicians in using CRP for the diagnosis of patients with bacterial infections presenting with relatively low CRP concentrations." (PMID 34863104, 2021). "Several studies showed that higher CRP values strengthen the differential diagnosis of acute bacterial infections over acute viral ones." (PMID 34863104, 2021). "In conclusion, among the biomarkers evaluated, CRP showed the best accuracy in differentiating viral from bacterial infections." (PMID 34574070, 2021). "The use of CRP to detect secondary bacterial infection is also feasible but the cut-off value is considerably elevated." (PMID 34021897, 2021).